AGPAT2 (1-acylglycerol-3-phosphate O-acyltransferase 2)
Diseases named in the same sentence as AGPAT2 in open-access papers (continued):
Sharing a sentence is not in itself a finding about the gene and the disease.
Berardinelli-Seip Syndrome (8 papers, 2011 to 2023). "In addition, we also found a second variant of interest in a gene associated with congenital generalized lipodystrophy type 1: AGPAT2 (chr9:139581758insCAG; NM_006412.3:c.51_52insGTC; NP_006403.2:p.X18Leu; rs201504151)." (PMID 26176221, 2015). "This is best exemplified by the role of AGPAT2 in the development of type 1 congenital generalized lipodystrophy (CGL) and is also manifested by recent studies highlighting the involvement of AGPATs in the physiology and pathology of various tissues and organs." (PMID 35008394, 2022).
Hepatic steatosis (8 papers, 2011 to 2023). Steatosis is a term used to denote lipid accumulation within hepatocytes. "The AGPAT2 deficient mice are hyperglycemic, hyperinsulinemic, hypoleptinemic, insulin-resistant and display liver steatosis." (PMID 35250856, 2022). "Instead of being caused primarily by high serum free fatty acid levels, hepatic steatosis in AGPAT2 mice could be explained by a tissue-autonomous function of AGPAT2." (PMID 21533227, 2011). "Studies have shown that, in AGPAT2 knock-out mice, activation of an alternative MAG pathway for TG biosynthesis leads to hepatic steatosis." (PMID 36978948, 2023). "In addition, for AGPAT2 and BSCL2 KO mice, leptin replacement or AT surgical implantation strongly improved the metabolic phenotype including insulin resistance, liver steatosis and renal injuries." (PMID 35250856, 2022). "Acetyl-CoA carboxylase 1 (ACC1), fatty acid synthase (FAS), 1-O-acylceramide synthase (ACS), 1-acyl-sn-glycerol-3-phosphate acyltransferase β (AGPAT2) and adipose triglyceride lipase (ATGL) have been reported to be crucial to TG metabolism in vitro and liver steatosis in vivo." (PMID 22675471, 2012). "Interestingly, AGPAT2 re-expression in the liver of total KO mice did not rescue the massive liver steatosis whereas leptin replacement did, as well as it improved glucose homeostasis." (PMID 35250856, 2022).
partial lipodystrophy (5 papers, 2016 to 2024). Loss and redistribution of subcutaneous and/or visceral adipose tissue from specific regions of the body. "In an adult female patient with clinical and metabolic features of partial lipodystrophy we identified via whole genome sequencing (WGS) a single complex AGPAT2 allele [V67M;V167A], functionally equivalent to heterozygosity." (PMID 30319454, 2018). "By using an intronic primer situated upstream from rs2236514 we were able to show that our patient is the first case of partial lipodystrophy associated with a single complex allele in AGPAT2." (PMID 30319454, 2018). "In the current study, a patient with partial lipodystrophy was identified with a single complex AGPAT2 allele, which is functionally equivalent to heterozygosity." (PMID 30319454, 2018).
hypertriglyceridemia (4 papers, 2021 to 2024). A laboratory test result indicating elevated triglyceride concentration in the blood. "Most patients had hypertriglyceridemia and DM, and 72.7% harbor AGPAT2 gene mutations (Subtype 1 CGL)." (PMID 34130736, 2021).
intellectual impairment (4 papers, 2014 to 2020). "Concerning genetic consequences, mutations in the AGPAT2 gene are associated with the occurrence of bone cysts, while mutations in the BSCL2 gene are associated with cognitive deficits and a higher incidence of premature death." (PMID 29864145, 2018).
Obesity (4 papers, 2017 to 2023). Accumulation of substantial excess body fat.
osteosarcoma (4 papers, 2010 to 2025). A usually aggressive malignant bone-forming mesenchymal neoplasm, predominantly affecting adolescents and young adults. "Accordingly, lncRNA OPI5-AS1, a competing endogenous RNA for miR-340-5p, had the opposite effect and increased AGPAT2 protein levels in osteosarcoma cell lines." (PMID 35008394, 2022). "In osteosarcoma, AGPAT2 expression analyzed by immunohistochemistry was increased in cancer compared to adjacent tissues." (PMID 35008394, 2022). "We sought to investigate the role of lysophosphatidic acid acyltransferase β (LPAATβ, aka, AGPAT2) in regulating the proliferation and growth of human osteosarcoma cells." (PMID 21152068, 2010). "In addition, in osteosarcoma cells, AGPAT2 expression levels positively correlated with cell proliferation and xenograft growth and an increase in cisplatin-resistant cells compared to control parental cells." (PMID 35008394, 2022). "Previously, the oncogenic role of AGPAT2, another member of the AGPAT gene family, has been reported in leukemia, pancreatic, and ovarian cancers, as well as in cisplatin chemoresistance in osteosarcoma." (PMID 40063560, 2025). "The miR-340-5p, which is downregulated in cisplatin-resistant osteosarcoma cell lines, targets the 3′ UTR of AGPAT2 and, although it does not affect mRNA levels, decreases the levels of AGPAT2 protein." (PMID 35008394, 2022).
ovarian carcinoma (4 papers, 2005 to 2025). A malignant neoplasm originating from the surface ovarian epithelium. "For example, AGPAT2 expression is elevated in ovarian cancer patients with aggressive ovarian cancers and associated with reduced overall survival." (PMID 25866768, 2015). "Furthermore, overexpression of AGPAT2 in ovarian cancer samples was associated with aggressive histology and higher tumor grade and linked to decreased overall and disease-free survival, especially in younger patients." (PMID 35008394, 2022). "The expression of AGPAT2 mRNA and/or protein, analyzed respectively by RT-PCR and immunohistochemistry, was increased in ovarian carcinomas compared to controls." (PMID 35008394, 2022). "Supporting the biological significance of the increased expression of AGPAT2 in ovarian cancer tissue samples, knockdown of AGPAT2 by siRNA decreased viability of ovarian cancer cells lines (SK-OV-3 and IGROV1)." (PMID 35008394, 2022). "Therefore, AGPAT2 could be a promising prognostic tool and possibly a target of directed therapy for ovarian cancer." (PMID 35008394, 2022).
cardiomyopathy (2 papers, 2015 to 2017). A disease of the heart muscle or myocardium proper. "This is particularly interesting, as BSCL2 patients frequently suffer from cardiomyopathy not seen with AGPAT2 deficiency in BSCL1 patients." (PMID 25737955, 2015).
cervical adenocarcinoma (2 papers, 2022). An adenocarcinoma arising from the cervical epithelium. "HIF1 was reported to regulate the expression of AGPAT2 (encoding an enzyme involved in the triacylglycerol biosynthetic pathway) in HCC and cervical adenocarcinoma cells." (PMID 36686803, 2022). "Furthermore, AGPAT2 knockdown reduced the lipid droplet content and reverted the resistance to therapy in cervical adenocarcinoma cells." (PMID 36686803, 2022).
acromegaly (1 paper, 2020). Acromegaly is an acquired disorder related to excessive production of growth hormone (GH) and characterized by progressive somatic disfigurement (mainly involving the face and extremities) and systemic manifestations. "This case of CGL type 1 (AGPAT2 deletions) with true acromegaly is the first to be reported in the literature." (PMID 32079542, 2020).
congenital generalized lipodystrophy (1 paper, 2015). An extremely rare autosomal recessive condition, characterized by an extreme scarcity of fat in the subcutaneous tissues. "A role for Agpat2 in triglyceride synthesis and adipocyte biology has emerged since the discovery of mutations in AGPAT2 caused an autosomal recessive form of congenital generalized lipodystrophy (CGL) type 1." (PMID 26086818, 2015).
COVID-19 (1 paper, 2021). A disease caused by infection with severe acute respiratory syndrome coronavirus 2. "Taken together, downregulation of AGPAT2 and DTX4 supports the accumulation of LPA and free fatty acids (FAs) and alters the excess lipid storage in the inert form of triglycerides in the cellular lipid droplets, which can be seen in the COVID-19 plasma lipidome." (PMID 34659373, 2021).
hepatocellular carcinoma (1 paper, 2022). A malignant tumor that arises from hepatocytes. "HIF-1, in addition to its other target genes, which mediate the adaptation of lipid metabolism under hypoxia, has been found to also regulate the transcription of AGPAT2 gene by binding directly to the AGPAT2 promoter in human hepatocellular carcinoma and adenocarcinoma cells." (PMID 35008394, 2022).
intellectual disabilities (1 paper, 2024). "Unlike AGPAT2 mutations, which primarily affect adipose tissue, BSCL2 mutations can impact various tissues, potentially contributing to intellectual disabilities due to Seipin's expression in the brain." (PMID 39131003, 2024).
melanoma (1 paper, 2025). A malignant, usually aggressive tumor composed of atypical, neoplastic melanocytes. "Notably, although multi-omics analyses have successfully constructed melanoma prognostic models, the functional roles and dynamic regulation of key genes such as AGPAT2 within the immune microenvironment remain to be fully elucidated." (PMID 41050070, 2025).
nephromegaly (1 paper, 2020). "The most common renal finding in CGL is nephromegaly, but renal lithiasis was also described in a 2-month-old Persian child who carried a nonsense mutation in exon 6 of AGPAT2 (c.685G > T, p.Glu229*)." (PMID 32280377, 2020).
polyneuropathy (1 paper, 2019). A disease or disorder affecting more than one nerve. "This case study suggests that in some genetic contexts, AGPAT2 mutations can also produce phenotypes with primary polyneuropathy." (PMID 30563316, 2019).
ZIKV infection (1 paper, 2022). "DGAT1, ACAT1, AGPAT1, and AGPAT2 mRNA levels were increased after ZIKV infection (albeit < 1.5-fold compared with the levels in the mock control), indicating that ZIKV infection promotes LD biosynthesis." (PMID 36405969, 2022). "Although the expression of the DGAT1, ACAT1, AGPAT2, and AGPAT1 genes, which are involved in LD biosynthesis, was activated, fatty-acid synthases (SCD1 and FASN, but not ACC1) were significantly downregulated during ZIKV infection." (PMID 36405969, 2022).
cancer (15 papers, 2005 to 2025). A tumor composed of atypical neoplastic, often pleomorphic cells that invade other tissues. "It is worth noting that associations of the AGPAT2 gene with the development of cancers have been described." (PMID 40508223, 2025). "AGPAT2 association to cancer has been extensively reported in several human cancers and its inhibition has been explored as a potential cancer therapy." (PMID 33050166, 2020). "Previous data in cancer cells indicated that PA synthesis by AGPAT‐2 (also known as LPPAT‐β) constitutes a mechanistic link between OA and mTOR activation." (PMID 38223199, 2024). "AGPAT2’s involvement in cancer is evident, with increased expression observed in ovarian cancer, correlating positively with cancer stage, grade, and mitotic index, indicating its potential prognostic value." (PMID 38893234, 2024). "An increase in PA after OA treatment has been shown to activate mTOR signaling in cancer cell lines and knockdown of AGPAT2 expression prevented the effect, suggesting that OA, when incorporated into PA, was a potent stimulator of mTOR activity." (PMID 38223199, 2024). "The profound effect of AGPAT2 expression on cancer cell proliferation suggested its possible use as a therapeutic target and led to the search and development of AGPAT2 inhibitors." (PMID 35008394, 2022). "In pancreatic cancer cells, AGPAT2 silencing resulted in the inhibition of cancer cell proliferation and anchorage-independent growth, possibly connected to the concurrent inhibition of the mTOR signaling pathway." (PMID 35008394, 2022). "Gpam, Agpat2, and Dgat1 are critical enzymes involved in TG biosynthesis and Gpam overexpression correlates with cancer cell migration." (PMID 32156004, 2020). "ACYLGLYCEROL-3-PHOSPHATE ACYLTRANSFERASE 2 (AGPAT2) promotes the survival and etoposide resistance of cancer cells under hypoxia." (PMID 31717838, 2019). "While several studies have suggested the association between enhanced transcription of AGPAT2 and certain cancers or inflammation-associated diseases, neither of them have described the influence of AGPAT1 isoform on cancer prognosis." (PMID 25749516, 2015). "Several lines of evidence have been reported concerning the relationship between the increased expression of AGPAT2 and several cancers, i.e., the augmented expression of AGPAT2 were observed in some human cancers." (PMID 25415055, 2014). "Furthermore, HIF-1 has the capacity to promote lipid droplet accumulation and enhance cancer cell viability under hypoxic conditions by directly targeting AGPAT2, an enzyme crucially involved in the glycerophospholipid/triacylglycerol biosynthesis pathway." (PMID 37954977, 2023). "The expression of AGPAT2, an enzyme involved in the glycerophospholipid/triacylglycerol biosynthesis pathway, has been suggested to promote survival and etoposide resistance of cancer cells, and to be directly involved in LD formation." (PMID 36139614, 2022). "Moreover, AGPAT2 expression is necessary for survival and proliferation of many types of cancer cells and xenografts." (PMID 35008394, 2022). "Furthermore, targeting of AGPAT2 by specific siRNAs or miRNAs affected cancer cell proliferation and chemoresistance." (PMID 35008394, 2022). "In addition to the roles in synthesis and storage of TAG, the sequential reactions of GPAT/AGPAT are involved in the synthesis of intracellular messenger PA, and the inhibitors of AGPAT2 are suggested as candidates for anti-cancer drugs." (PMID 25415055, 2014). "However, the role of AGPAT2 in cancer is out of the scope of this review." (PMID 40508223, 2025). "Given these factors, it has been possible to correlate the participation of the AGPAT2 gene in malignancies since 1-AGPAT 2 is an indispensable enzyme for lipid metabolism, which is necessary for cancer development." (PMID 40508223, 2025).
cancer (continued). "It should be noted that while seipin was knocked out, AGPAT2 was knocked down, because the AGPAT2 knock-out cancer cell lines were very sick in our hands and therefore not used." (PMID 34824276, 2021).
tumor (6 papers, 2005 to 2022). "A cDNA microarray analysis showed that AGPAT2 was among the genes upregulated in primary gastric cancerous tissue samples compared to tumor-adjacent tissue." (PMID 35008394, 2022). "AGPAT2 inhibitors have been shown to induce growth arrest, apoptosis, or necrosis in various tumor cell lines." (PMID 25415055, 2014). "The antitumor activities of AGPAT2 inhibitors were also demonstrated in mice bearing tumor xenografts." (PMID 25415055, 2014).
infection (2 papers, 2019 to 2024). The state of being infected such as from the introduction of a foreign agent such as serum, vaccine, antigenic substance or organism. "Patterns of DEGs in MDM of homozygotes with either the BSCL2 or AGPAT2 mutations clustered together and separately from WT control samples, regardless of their infection status." (PMID 38755198, 2024). "Depletion of either AGPAT1 or AGPAT2 increased aminophospholipids and partially recapitulated DENV-induced reconfiguration before infection in vitro." (PMID 31815960, 2019). "Infection in AGPAT1-depleted cells, but not in AGPAT2-depleted cells, mostly increased aminoPLs as compared to infected wild-type cells." (PMID 31815960, 2019).
cardiovascular disease (1 paper, 2020). "We describe two unrelated patients with type 1 CGL due to Leu124Serfs*26, a novel AGPAT2 frameshift mutation, presenting as early cardiovascular disease." (PMID 32280377, 2020).
metabolic disease (1 paper, 2019). A congenital disorder (due to inherited enzyme abnormality) or acquired (due to failure of a metabolically important organ) disorder resulting from an abnormal metabolic process. "Overall, the novel findings regarding the regulation of AGPAT2 and function of seipin demonstrate the power of our morphometric approach to identify new mechanistic insights regarding genes important for human metabolic disease." (PMID 30940487, 2019). "We tested this approach with metabolic disease genes expressed in adipocytes, identifying and subsequently validating novel interactions between BSCL2 and PLIN1 (protein–protein) as well as CEBPA and AGPAT2 (genetic regulatory)." (PMID 30940487, 2019).
AGPAT2 also shares sentences with these, for which no sentence is quoted: Berardinelli-Seip congenital lipodystrophy type 2 (3 papers); leukemia (3); dyslipidemia (2); familial partial lipodystrophy (2); lipoma (2); acquired lipodystrophy (1); adenocarcinoma (1); autosomal recessive disease (1); bone cysts (1); CANDLE syndrome (1); colon cancer (1); congenital generalized lipodystrophy type 3 (1); cystadenoma (1); diabetic polyneuropathy (1); dyslipidaemia (1); familial partial lipodystrophy type 2 (1); genetic disorder (1); Huntington disease (1); hyperinsulinism (1); hyperlipidemia (1); hypotrichosis (1); laminopathies (1); laryngeal squamous cell carcinoma (1); left ventricular hypertrophy (1); Lipoatrophy (1); mandibuloacral dysplasia (1); neurodegenerative disease (1); neurological disorders (1); ovarian tumours (1); pancreatic cancer (1).
A further 6 diseases each share a sentence with AGPAT2 in 1 paper.